MIR6782 (microRNA 6782)
Synonyms: hsa-mir-6782
Gene: MicroRNA gene on chromosome 17 (44,207,771 to 44,207,839, reverse strand). Ensembl gene ENSG00000275107.
Homologues: Orthologues: chimpanzee MIR6782 (100% identical).